RNF151 (ring finger protein 151)
Description:
May be involved in acrosome formation of spermatids.
Tractability: No criterion of Open Targets' tractability assessment is met for any kind of drug.
Gene: Protein-coding gene on chromosome 16 (1,966,823 to 1,968,975, forward strand). Ensembl gene ENSG00000179580.
Subcellular location: Cytoplasm; Nucleus
Subcellular location (Human Protein Atlas): Cytosol; Nuclear speckles; Vesicles
Gene Ontology:
Molecular function: protein binding; enzyme binding; zinc ion binding
Cellular component: cytoplasm; nucleus
Genetic constraint (gnomAD): Loss-of-function variants: 11 observed, 11.26 expected, observed/expected ratio (o/e) 0.98, 90% interval 0.61 to 1.6. The synonymous counts are far from expectation, so gnomAD's model fits this gene poorly and the ratio says little. Missense variants: 372 observed, 315.07 expected, observed/expected ratio (o/e) 1.18, 90% interval 1.08 to 1.29. Synonymous variants: 172 observed, 126.61 expected, observed/expected ratio (o/e) 1.36, 90% interval 1.2 to 1.54.
Homologues: Orthologues: chimpanzee RNF151 (97% identical), macaque RNF151 (91% identical), pig RNF151 (79% identical), dog RNF151 (78% identical), mouse Rnf151 (67% identical), rat Rnf151 (66% identical), guinea pig RNF151 (64% identical), zebrafish rnf151 (36% identical), tropical clawed frog RNF151 (34% identical), Drosophila melanogaster CG9014 (21% identical). Paralogues in human: RNF41 (21% identical).
Diseases named in the same sentence as RNF151 in open-access papers:
RNF151 is named in the same sentence as 3 diseases in open-access papers, as found by Europe PMC text mining. Sharing a sentence is not in itself a finding about the gene and the disease. The quoted sentences say what the papers report.
avian influenza (1 paper, 2026). Infection of domestic and wild fowl and other birds with influenza A virus. "Although little is known about RNF151 in chickens, it has been reported as downregulated during infection with highly pathogenic avian influenza." (PMID 41595482, 2026).
RNF151 also shares sentences with these, for which no sentence is quoted: cancer (1 paper); infection (1).